NLRP3 (NLR family pyrin domain containing 3)
Diseases named in the same sentence as NLRP3 in open-access papers (continued):
Sharing a sentence is not in itself a finding about the gene and the disease.
cutaneous melanoma (4 papers, 2021 to 2023). A primary melanoma arising from atypical melanocytes in the skin. "The NLRP3 inflammasome–Interleukin‐1β axis was recently proposed as a therapeutic target for cutaneous melanoma." (PMID 36707938, 2023). "Further, both uveal and cutaneous melanoma showed very low NLRP3 mRNA levels when compared to the monocyte cell line THP‐1 (P < 0.001)." (PMID 36707938, 2023). "This work was to investigate mechanism by which mir-22 targeting nod-like receptor protein 3 (NLRP3) inflammasome affected activity of human skin malignant melanoma (MM) A375 cells." (PMID 35874899, 2022). "In humans, analyses of the TCGA dataset revealed positive mRNA correlations from cutaneous melanoma biopsies for expression of NLRP3 and IL‐6 (p=4.86e-20), IL‐6 and the STAT3 target gene Socs3 (p=1.82e-62), IL-1β and Socs3 (p=1.71e-31)." (PMID 34531850, 2021). "Analysis of cancer genome datasets (TCGA and GTEx) revealed greater NLRP3 and IL-1β expression in cutaneous melanoma samples (n = 469) compared to normal skin (n = 324), with a highly significant correlation between NLRP3 and IL-1β (P < 0.0001)." (PMID 33649199, 2021). "Analyses of the Cancer Genome Atlas (TCGA) and the GTEx datasets exhibited highly significant increases in NLRP3 and IL-1β expression in cutaneous melanoma samples compared to normal skin." (PMID 33649199, 2021). "Recent studies suggested that the NLRP3 inflammasome could be a therapeutic target for cutaneous melanoma (CM), but the role of NLRP3 in UM remains unknown." (PMID 36707938, 2023). "Therefore, miR-22 may target and inhibit the activation of the NLRP3 inflammasome to reduce the activity of cutaneous malignant melanoma A375 cells." (PMID 35874899, 2022).
demyelinating disease (4 papers, 2012 to 2023). A broad group of disorders that affect the myelin sheaths that cover the neurons. "In recent years the therapeutic potential of NLRP3 inhibition to address various neurodegenerative and demyelinating disorders has gained increasing attention." (PMID 37575265, 2023). "Because the levels of IL-6 and T cells in the CNS are known to play important roles in the pathogenesis of TMEV-induced demyelinating disease, the signals downstream of the NLRP3 inflammasome are likely to be involved in the pathogenesis of TMEV-induced, immune-mediated demyelinating disease." (PMID 28445497, 2017). "However, the signaling effects of prostaglandin E2 (PGE2) downstream of the NLRP3 inflammasome on the immune responses to viral determinants and the pathogenesis of demyelinating disease are unknown." (PMID 28445497, 2017).
Dengue hemorrhagic fever (4 papers, 2022 to 2025). A serious condition caused by Dengue virus infection. "The authors concluded that the NLRP3 inflammasome contributes to disease and may also be a therapeutic target for treating Dengue Hemorrhagic Fever." (PMID 36298668, 2022). "In addition, both DENV EIII and NS1 proteins can induce pyroptosis through the inflammasome NLRP3, it further causes the typical manifestations of DHF (dengue hemorrhagic fever) such as vascular damage, liver dysfunction, thrombocytopenia, and hemorrhage." (PMID 35154151, 2022).
dermatomyositis (4 papers, 2022 to 2025). Dermatomyositis (DM) is a type of idiopathic inflammatory myopathy characterized by evocative skin lesions and symmetrical proximal muscle weakness. "Yin Xi’s research group reported that compared to healthy controls, patients with polymyositis (PM) and dermatomyositis (DM) showed elevated levels of NLRP3, IL-1β, and IL-18 mRNA in muscle fiber tissues, as well as increased expression of NLRP3 and caspase-1 p20 protein subunit." (PMID 39723212, 2024).
encephalomyelitis (4 papers, 2023 to 2025). Inflammation of the brain and the spinal cord. "Progression of encephalomyelitis in the spinal cord was accompanied by increased expression of NLRP3, whereas loss of NLRP3, Casp1, ASC, or IL-1β in mice led to resistance to encephalomyelitis." (PMID 36669831, 2023). "MCC950/CP-456,773 is a potent NLRP3 inhibitor; it has been shown to be effective in a mouse model of encephalomyelitis with a constitutively active NLRP3 mutant." (PMID 37507935, 2023). "Treatment of mice with MCC950 blocked NLRP3 activation at a nanomolar concentration, which reduced IL-1β production and attenuated the severity of experimental encephalomyelitis in vivo." (PMID 36669831, 2023).
Giardia infection (4 papers, 2021 to 2023). "Overall, the results of the present study revealed that alpha-2 and alpha-7.3 giardins trigger host NLRP3 inflammasome activation and decrease G. duodenalis infection ability in mice, which are promising targets for the prevention of giardiasis." (PMID 36869360, 2023). "However, the exact PAMPs in GEVs that are involved in NLRP3 inflammasome-regulated inflammation and the role of the NLRP3 inflammasome in giardiasis remain to be elucidated." (PMID 36869360, 2023). "However, the exact pathogen-associated molecular patterns in G. duodenalis EVs (GEVs) involved in this process and the role of the NLRP3 inflammasome in giardiasis remain to be elucidated." (PMID 36869360, 2023). "This study demonstrated that GEVs could be internalized into primary mouse peritoneal macrophages, regulate host cell innate immunity via TLR2 and NLRP3 inflammasome signaling pathways, and may provide new targets against giardiasis." (PMID 33798196, 2021). "However, limited research focus on the immune mechanisms mediated by the intracellular NLRs in extracellular pathogen of G. duodenalis except for a newly research, which reports that G. duodenalis can attenuate giardiasis in vivo via NLRP3." (PMID 33798196, 2021). "It has been reported that Giardia can mediate peritoneal macrophage pyroptosis via NLRP3/caspase-1/GSDMD in mice, contributing to the host resistance to Giardia infection and pathogenesis." (PMID 37821972, 2023). "In the present study, we confirmed the involvement of A20-mediated NLRP3 deubiquitination in inflammasome activation, CASP1 and GSDMD cleavage, and IL-1β and IL-18 release during Giardia infection." (PMID 34943932, 2021). "It is, therefore, worthwhile to examine the correlation between noninvasive Giardia infection, TLR-mediated recognition of parasite PAMPs, NLRP3 deubiquitination, and the activation and regulation of inflammasomes and pyroptosis." (PMID 34943932, 2021).
HCMV infection (4 papers, 2019 to 2025). "Whether HCMV infection is sensed by the AIM2 or the NLRP3 inflammasome, and whether UL83 or UL84 inhibits inflammasome activation, cytokine release, and pyroptosis will have to be clarified in future studies." (PMID 38278864, 2024).
head and neck cancer (4 papers, 2017 to 2024). A primary or metastatic malignant neoplasm affecting the head and neck. "Further research is needed to fully understand the mechanisms underlying NLRP3 inflammasome activation and its impact on head-and-neck-cancer pathophysiology." (PMID 39769450, 2024). "In this study, we investigated purinergic receptor P2X7 and NACHT, LRR and PYD domains-containing protein 3 (NLRP3) inflammasome expressions, and their role in head and neck cancer." (PMID 28430665, 2017). "Hence, NLRP3 inflammasome can be a potential target aimed at CSCs in the development of novel approaches for head and neck cancer therapy." (PMID 28865486, 2017).
Heat Stroke (4 papers, 2018 to 2024). A condition caused by the failure of body to dissipate heat in an excessively hot environment or during PHYSICAL EXERTION in a hot environment. "In summary, EGR1 emerges as a pivotal regulator of HMOX-1 expression in KC2, orchestrating ferroptosis and NLRP3 inflammasome activation, thereby contributing to liver injury in the context of heat stroke conditions." (PMID 39309491, 2024). "This study aimed to investigate the effect of CNS NLRP3 inflammasome in heat stroke in endotoxemic mice." (PMID 34092247, 2021). "So as to comprehensively understanding the role of NLRP3 inflammasome in heat stroke, Nlrp3 knockout mice were used." (PMID 34092247, 2021). "In this study, we first reported that NLRP3 inflammasome activation mediated neuroinflammation as a driving mechanistic force in heat stroke pathology, especially when it was exacerbated by prior infection." (PMID 34092247, 2021). "By using NLRP3 gene knockout mice, this study for the first time revealed the involvement of CNS NLRP3 inflammasome activation in above mechanism by alleviating heat stroke which induced hypothalamic neuronal inflammation." (PMID 34092247, 2021). "The use of Nlrp3 knockout mice enhanced heat tolerance and alleviated heat stroke-induced death by reducing mice hypothalamus IL-1β production with prior infection condition." (PMID 34092247, 2021). "Recent studies suggested that NLRP3 inflammasome played an important role in the pathophysiology of heat stroke." (PMID 34092247, 2021). "This study elucidates the intricate molecular mechanisms underpinning heat stroke-induced liver injury, highlighting the diverse responses of Kupffer cell (KC) subsets and the pivotal role of HMOX-1 in orchestrating ferroptosis in KCs, particularly in KC2, and NLRP3 inflammasome activation." (PMID 39309491, 2024). "In this study, we found that short-term heat stoke alone failed to activate the NLRP3 inflammasome, whereas heat stroke in combination with even minor LPS pretreatment greatly activated NLRP3 inflammasome in mice hypothalamus which was further confirmed by immunofluorescence staining assay." (PMID 34092247, 2021).
hidradenitis suppurativa (4 papers, 2020 to 2025). A chronic suppurative and cicatricial disease of the apocrine glands occurring chiefly in the axillae in women and in the groin and anal regions in men. "Activation of Notch and NLRP3 inflammasome signaling has been reported in hidradenitis suppurativa, a chronic inflammatory condition that is accompanied by severe tissue destruction and scarring." (PMID 33126764, 2020).
hypertensive nephropathy (4 papers, 2023 to 2025). Kidney damage that results from chronically elevated blood pressure; complications include glomerular damage resulting in proteinuria and hematuria. "Looking ahead, interventions aimed at the NLRP3 inflammasome may offer novel therapeutic targets for the treatment of hypertensive nephropathy." (PMID 40841164, 2025). "Moreover, the intricate interplay between NLRP3 and gut microbiota plays a role in the pathological progression of hypertensive nephropathy." (PMID 40841164, 2025). "New therapies directed toward the NLRP3 inflammasome are increasingly being recognized for their potential to decrease both AKI and CKD, such as hypertensive nephropathy." (PMID 40806733, 2025).
hypertriglyceridemia (4 papers, 2019 to 2024). A laboratory test result indicating elevated triglyceride concentration in the blood. "Hypertriglyceridemia, as a result, can provoke a new systemic inflammation and potentiating a pre-existing one because it is considered an activator of the NLRP3 inflammasome." (PMID 38449886, 2024). "In animal experiments, the ORG mice developed proteinuria, podocyte injury, and hypertriglyceridemia, accompanied with deregulated lipid metabolism, renal ectopic lipid deposition, activation of NOD-like receptor protein 3 (NLRP3) inflammasome, and secretion of IL-1β of the kidney." (PMID 31097920, 2019).
immunotoxicity (4 papers, 2022 to 2024). "Furthermore, the immunotoxicity of Cr(VI) was associated with the activation of the NF-κB signaling pathway and NLRP3 inflammasome by oxidative stress." (PMID 35935959, 2022). "Mycotoxin-induced nephrotoxicity, hepatotoxicity, and immunotoxicity are closely related to the NLRP3 inflammasome, making it a likely target for pharmacotherapy." (PMID 39057975, 2024). "In chicken liver, AFB1 significantly induced the expression of TNF-α, IL-6, IL-1β, iNOS, COX-2, NLRP3, caspase-1, -3, and -11, which resulted in immunotoxicity." (PMID 39057975, 2024). "Upcoming research will further illuminate the potential of the NLRP3 inflammasome to act as a sensor of MNP immunotoxicity." (PMID 37143682, 2023). "In summary, this study for the first time reported the activation of NLRP3 inflammasome in macrophages as a critical event of the Mn2+-induced immunotoxicity." (PMID 35130615, 2022).
intestinal infection (4 papers, 2022 to 2025). "In the absence of any intestinal infection, a low level of NLRP3 is expressed in intestinal mucosal epithelial cells and immune cells." (PMID 36903391, 2023). "In the absence of intestinal infection, the expression of NLRP3 in intestinal mucosal epithelial cells and macrophages is deficient." (PMID 35448938, 2022).
irritable bowel syndrome (4 papers, 2020 to 2025). Irritable bowel syndrome (IBS) is a chronic functional condition of the lower gastrointestinal (GI) tract characterized by abdominal pain or discomfort and disordered bowel habit (diarrhea, constipation, or fluctuation between the two). "In addition, Bifidobacterium spp. can also alleviate visceral hypersensitivity in irritable bowel syndrome by inhibiting NLRP3." (PMID 36038927, 2022). "In addition, probiotics might also reduce the visceral hypersensitivity of irritable bowel syndrome by inhibiting NLRP3." (PMID 36038927, 2022).
leptospirosis (4 papers, 2017 to 2022). A contagious bacterial infection caused by spirochetes of the genus Leptospira. "Consistent with IL-1β found in blood of leptospirosis patients, another study showed that IL-1β and IL-18 were also produced in human cells through NLRP3 activation." (PMID 35937697, 2022). "Then, a cascade of inflammation is activated in the renal tubular cells, as leptospirosis induces interleukin (IL)-1β and IL-18 secretion from human macrophage cells through reactive oxygen species and cathepsin B mediated-NLRP3 inflammasome activation." (PMID 35203344, 2022). "In this study, we show that treatment with LPS promoted the gene expressions of TLR2, TLR4, NLRP3 and downstream cytokines, all of which would help control leptospirosis." (PMID 31914888, 2020). "Although some studies researched the relationship of NLRP3 inflammasome and leptospira, the role of NLRP3 inflammasome in the process of leptospirosis is still unclear." (PMID 28791016, 2017).
liver failure (4 papers, 2014 to 2022). A liver disease characterized by the liver losing or has lost all of its function. "NLRP3 inflammasome-deficient mice, such as Caspase1−/−, Asc−/−, and Nlrp3−/− mice, showed comparably reduced induction of liver failure to Tlr9−/− mice." (PMID 26549942, 2015). "ACLF is characterized by ROS production; ROS stimulates the NLRP3 inflammasomes, which regulate a variety of physiological responses and play a key role in liver failure." (PMID 35123412, 2022). "In fact, a recent report has shown protection against D-galactosamine- and lipopolysaccharide-induced acute inflammation and liver failure by HO1 overexpression through suppression of the NLRP3 signaling pathway." (PMID 24997191, 2014).
macular degeneration (4 papers, 2021 to 2024). Loss of vision in the central portion of the retina (macula), secondary to retinal degeneration. "Activated in response to various endogenous DAMPs including ATP, increased Cx-hemichannel activity has been linked to NLRP3-mediated inflammation and activation of multiple cell types in various pathologies, including macular degeneration retinopathy and Alzheimer’s." (PMID 37770948, 2023). "Here, we examine the evidence for PRRs, TLRs2/3/4, and NLRP3-inflammasome pathways in macular degeneration pathogenesis." (PMID 38443987, 2024).
malnutrition (4 papers, 2022 to 2023). Inadequate nutrition resulting from poor diet, malabsorption, or abnormal nutrient distribution. "The current study showed that MR prevents LPS-induced ALI, including the inflammatory response, inflammatory cell infiltration, and alveolar epithelial cell injuries without malnutrition via upregulating the CSE/H2S pathway, which is likely associated with inhibition of the TLR4/NF-κB/NLRP3 pathway." (PMID 35057502, 2022).
mental disorder (4 papers, 2019 to 2024). A disease that has its basis in the disruption of mental process. "In fact elevated level of IL-1β and IL-18 in biological fluids is a sign on Nlrp3 inflammasome activation and has been reported as useful diagnostic marker in several mental disorders." (PMID 31020518, 2019). "Our group has previously shown that, in a cohort of low-functioning individuals with serious mental disorders, there is increased expression of genes associated with the NLRP3 inflammasome, a known sensor of metabolic perturbations, as well as increased levels of IL-1-family cytokines." (PMID 34899431, 2021). "Compared to common cytokines like INF-γ, IL-6, and TNF-a, NLRP3 and IL-18 have rarely been studied in clinical studies of mental disorders." (PMID 38627683, 2024). "Meanwhile, many experiments also proved that NLRP3 is a key target of mental disorders." (PMID 36267291, 2022). "In the current study, we aim to investigate the link between inflammatory pathways, including the NLRP3 inflammasome, selected markers of inflammation, previously identified markers of neuroinflammatory events, and the lipidome in low-functioning individuals with serious mental disorders." (PMID 34899431, 2021). "However, not much research focused on the NLRP3 inflammasome, which plays a critical role in neuroinflammation response to develop mental disorders." (PMID 36267291, 2022).
monocytic leukemia (4 papers, 2018 to 2024). "THP‐1 cells expressing high levels of NLRP3 are a well‐established human monocytic leukemia cell line that has been extensively used as a model system to study pyroptosis." (PMID 38804602, 2024).
mucositis (4 papers, 2017 to 2023). Mucositis is inflammation and damage of the mucous membranes lining the mouth and other parts of the gastrointestinal (GI) tract. "Interestingly, the protective effect of melatonin in mitochondria was associated with inhibition of the NLRP3 inflammasome and decreased mucositis signals." (PMID 28403142, 2017). "Regarding IBDs, GDF11 was able to ameliorate UC in a mice model through inhibition of NLRP3 inflammasome complex, the main responsible for the maturation of pro-inflammatory cytokine IL-1β and markedly present in mucositis induced by 5-FU." (PMID 37138633, 2023). "Moreover, the NF-κB pathway activates the NLRP3 inflammasome complex which is the main responsible for the maturation of pro-inflammatory cytokine IL-1β and is markedly present in mucositis induced by 5-FU." (PMID 37138633, 2023). "Assays and studies on the tongues of irradiated rats showed that mitochondrial ROS production plays a role in mucositis and is influenced by the NF-kappa-B and NLRP3 activation (both are known to activate inflammatory pathways that increase the expression of genes responsible for causing mucositis)." (PMID 29121966, 2017).
muscle atrophy (4 papers, 2021 to 2025). The loss of muscle tissue due to inactivity or disease. "Several studies have recently examined the vital role of the NLRP3 inflammasome in muscle atrophy 23, 24, but fewer studies have explored its role in denervation." (PMID 36593964, 2023). "Findings from recent studies suggest that the nucleotide-binding and oligomerisation domain (NOD)-like receptor family pyrin domain containing 3 (NLRP3) inflammasome, a regulator of inflammation, may be crucial in the development of skeletal muscle atrophy." (PMID 36405697, 2022). "Taken together, these data suggest that NLRP3 may potentially be a therapeutic target for the treatment of skeletal muscle atrophy." (PMID 34537816, 2021). "Moreover, LPS/ATP treatment also resulted in increased expression of atrophy markers, Atrogin-1 and MuRF1, indicating that trimetazidine may attenuate dexamethasone-induced muscle atrophy via inhibiting NLRP3-mediated pyroptosis." (PMID 34537816, 2021).